BRAF (B-Raf proto-oncogene, serine/threonine kinase)
Diseases named in the same sentence as BRAF in open-access papers (continued):
Sharing a sentence is not in itself a finding about the gene and the disease.
melanoma (continued). "BRAF mutational status from all thyroid (n = 8) and melanoma (n = 23) cases were correctly detected by all observers." (PMID 26496026, 2015). "In this respect, miR-192 downregulation in MPM is similar to that observed for colorectal and childhood renal cancer, and lower miR-193a-3p reflects findings in oral squamous cell carcinoma, acute myeloid leukemia, lung cancer and BRAF-mutated melanoma." (PMID 26125439, 2015). "On the other hand, in melanoma cells harboring BRAF mutations, only the MEK/ERK pathway results to be overactivated." (PMID 26225426, 2015). "In this study, mutations at codon 594 constituted the second most common BRAF mutations in NSCLCs (7/33, 21 %), CRCs (4/34, 12 %) and melanomas (4/68, 5.9 %)." (PMID 26498038, 2015). "Among these driver genes, the BRAF mutation at position 600 (BRAFV600) occurs in approximately 50% of melanoma patients, and among them, V600E accounts for approximately 79%." (PMID 25890285, 2015). "BRAF mutations have initially been described in malignant melanoma where 40%–60% of tumors harbor an activating V600E BRAF mutation." (PMID 26018876, 2015). "For melanoma, the activating V600 mutations, including V600E, are associated with increased sensitivity to BRAF inhibitors such as vemurafenib and dabrafenib." (PMID 26101870, 2015). "The identification of a selection marker for treatment, such as a BRAF mutation in melanoma, offers the ability to prospectively identify patients more likely to benefit from certain therapies." (PMID 25682878, 2015). "What has been shown is that S73 phosphorylation is required for its interaction with the acetyltransferase p300 in human melanoma cells carrying a BRAF mutation, an observation that suggests a role of MAPK signalling in MITF acetylation." (PMID 25818589, 2015). "Although this stratification is relevant, controversy exists regarding the prognostic significance of classifying melanomas based only on BRAF and NRAS mutations." (PMID 25909218, 2015). "In particular, metformin induces cell-cycle arrest in the G0/G1 cell-cycle phase and a strong inhibition of cell viability by induction of autophagy and apoptosis in different melanoma cells independently of the BRAF or NRAS mutational status." (PMID 26322273, 2015). "CheckMate 067 enrolled 945 treatment-naïve patients with advanced melanoma who were stratified according to disease stage, BRAF mutation status, and programmed death ligand 1 (PD-L1) expression." (PMID 26518223, 2015). "The genetic lesions in melanoma, including NRAS and BRAF mutations, are well characterized, and activated BRAF kinase has been demonstrated to be an effective drug target for melanoma therapy." (PMID 25642713, 2015). "After demonstrating its efficacy, vemurafenib was approved for the treatment in patients with BRAF-mutated melanoma by the US Food and Drug Administration (FDA) in 2011." (PMID 29061943, 2015). "BRAF mutations play a critical role in melanoma oncogenesis and have thus been shown to be a promising target for molecular therapeutic approaches." (PMID 26462148, 2015). "Activating mutations in BRAF are among the most frequent mutations in melanoma, and somatic mutations have also been identified in genes encoding the transcriptional machinery that drives neural crest and melanocyte development." (PMID 25670789, 2015). "These investigators demonstrated that, of the six melanoma cell lines (carrying BRAF mutations) when treated with increasing doses of PLX4032, three cell lines (M288, SKEML28 and M14) attained resistance." (PMID 26393652, 2015). "It has been demonstrated that IHC analysis using anti-BRAF antibody was highly sensitive and specific for detection of BRAF V600E mutation in melanoma." (PMID 25784655, 2015). "Recently, two phase III studies demonstrated the superiority of a combination of dabrafenib and trametinib over a single agent BRAF inhibitor in treatment-naïve patients with advanced melanoma harboring a V600 BRAF mutation." (PMID 25962795, 2015).
melanoma (continued). "Melanoma harboring BRAF mutations frequently develop resistance to BRAF inhibitors, limiting the impact of treatment." (PMID 26497853, 2015). "Less than 10 years later, the small-molecule kinase inhibitors vemurafenib and dabrafenib were approved for use in BRAF mutation-positive melanomas, as the front-runners in a competition between numerous companies engaged in cancer drug discovery." (PMID 25422355, 2015). "Mutated BRAF is a new target for the treatment of advanced melanoma and provides an important opportunity for new therapies." (PMID 26705496, 2015). "BRAF inhibitors are widely used to treat patients with BRAF mutated melanoma, but most metastatic patients with initial tumor response develop acquired resistance with a median PFS of less than 7 months." (PMID 26141748, 2015). "NRAS mutated patients developed LM within 5 yrs from primary melanoma with larger lesions compared with BRAF (mean diameter 3.3 ± 2.2cm vs 1.9 ± 1.1cm, p = 0.2)." (PMID 26305188, 2015). "Disease prognosis for melanoma patients bearing BRAF V600 mutations has drastically improved in relation to the introduction of BRAF inhibitors (BRAFi) two of which, vemurafenib and dabrafenib, have already been approved by FDA." (PMID 26208478, 2015). "To validate the NGS platform we first analyzed seven independent tumor FFPE samples from lung, colon and melanoma with known mutations in BRAF (V600E), KRAS (G12S, G13D), and EGFR (L858R and E746_A750del)." (PMID 26124082, 2015). "One mechanism of resistance of the melanoma-associated BRAF kinase to its small molecule inhibitor vemurafenib is by point mutations in its intron 8 resulting in exons 4–8 skipping." (PMID 26697165, 2015). "The low-activity BRAF mutations G469E/D594G that signal through CRAF were later identified in a panel of melanoma cell lines." (PMID 24743024, 2014). "Although cancers like melanoma or pancreatic adenocarcinoma are driven by point mutation of oncogenes BRAF and KRAS, respectively, EAC appears to obtain its oncogenic drive through amplification." (PMID 25351503, 2014). "In melanoma, the existence of a BRAF mutation is a main predictor for successful BRAF-targeted therapy." (PMID 24941944, 2014). "Most recent examples include ALK inhibitors in non-small cell lung cancer with an ALK rearrangement or BRAF inhibitors in melanoma with a BRAF mutation." (PMID 24931142, 2014). "An example is the relative insensitivity of BRAF-mutant colon cancer to BRAF inhibition, despite the presence of the same mutation that confers sensitivity in melanoma." (PMID 25286031, 2014). "Taken together, the data suggest that PTEN deficiency is a promising prognostic marker in BRAF wild type melanomas." (PMID 24830350, 2014). "An in vitro study with a single BRAF-mutant melanoma line showed that BRAF-inhibitor treatments were associated with reduced expression of RND3, an antagonist of RHOA activation, and elevated RHOA-dependent signaling." (PMID 24743024, 2014). "This is even more relevant for acral and mucosal melanomas that should be investigated for both BRAF and KIT mutations at the first step." (PMID 24591764, 2014). "Nevertheless, BRAF mutations select patients with advanced melanoma for treatment with anti-BRAF agents (vemurafenib-PLX4032 and dabrafenib-GSK2118436)." (PMID 25361007, 2014). "Nazarian and co-workers showed that melanomas harboring a BRAF (V600E) mutation eventually become resistant to the RAF-selective inhibitor, PLX4032, by activation of an alternative survival pathway mediated by PDGFRβ." (PMID 24885200, 2014). "For example, the survival of patients with melanoma and the BRAF V600 mutation improved when treated with a combined BRAF and MEK inhibitor." (PMID 24796583, 2014). "BRAF mutations occur in approximately 50% to 60% ofmelanomas; approximately 95% of melanomas that harbor a BRAF mutation are characterized as having aBRAF V600E mutation." (PMID 25089220, 2014).
melanoma (continued). "A large phase III trial, BRIM 8, is being conducted to explore the safety and efficacy of single-agent vemurafenib as adjuvant therapy in patients with BRAF-mutant resected high-risk melanoma (NCT01667419)." (PMID 26328215, 2014). "Genetic and pharmacological studies have shown that disruption of the BRAF-MEK-ERK pathway blocks the growth of melanoma cells harboring an oncogenic BRAF mutation and thus represents an attractive therapeutic target." (PMID 24550252, 2014). "This BRAF mutation, V600E, which has been detected in 50 to 60% of human melanomas, results in activation of the kinase; this drives the downstream MEK-ERK kinase signaling cascade, leading to proliferation and survival of cancer cells." (PMID 25031620, 2014). "This clinical experience suggests that (i) patients with BRAFV600DK601del-mutation-positive melanoma can be treated successfully with the oral BRAF inhibitor vemurafenib and (ii) molecular screening in this context should encompass rare and complex mutations." (PMID 25265970, 2014). "Cytotoxicity of free vemurafenib and encapsulated vemurafenib was assessed using Colo829 melanoma cells, which contain the BRAF V600E mutation." (PMID 24919932, 2014). "In our study, we contributed to provide additional clues about the prevalence of alterations in some candidate genes (with particular attention to BRAF mutations) among synchronous or asynchronous multiple primary melanomas." (PMID 24885594, 2014). "Mutations in BRAF has been found in different kinds of cancers, predominantly melanoma, metastatic colorectal cancer and papillary thyroid cancer." (PMID 24979348, 2014). "Several groups have reported a strong inverse correlation between age and BRAF mutation prevalence, and within our primary melanoma subgroup we also observed a significantly higher BRAF mutation rate among young patients (≤55 years)." (PMID 25526463, 2014). "This is the case in HER2/neu over-expressing or amplified breast or gastric cancers or BRAF-mutated melanoma." (PMID 24777052, 2014). "The search for driver mutations in melanoma continues, with the previously identified subtypes involving BRAF, NRAS, KIT, GNAQ, and GNA11 expanded recently to include NF1 and telomerase." (PMID 24743024, 2014). "BRAF(V600E) mutation is frequently associated with melanoma, where it seems to play a critical role in the malignancy process and can be effectively treated using vemurafenib." (PMID 24910641, 2014). "Combination therapy with BRAF and MEK inhibition is currently in clinical development for the treatment of BRAF mutated malignant melanoma." (PMID 25309914, 2014). "Sixty-two paired samples from 54 (51%) patients showed discrepancies in BRAF/cKIT/CyclinD1 mutation patterns between first and subsequent primary melanomas." (PMID 24885594, 2014). "These include BRAF V600 mutation for melanoma, EGFR mutation and ALK fusion for lung cancer, HER2 amplification or overexpression for breast cancer, and KRAS mutation for colorectal cancer." (PMID 25593991, 2014). "Mutated, activated BRAF occurs in about 7% of all human cancers, but about 50% of melanomas contain BRAF mutation at V600." (PMID 24722523, 2014). "In summary, our findings identify the mutually exclusive NRAS and BRAF mutation status as possible predictive marker for the response to DNA synthesis inhibitors such as antifolate drugs in melanoma patients." (PMID 24941944, 2014). "Lastly, BREAK-3 was a large multicenter open-label randomized phase III clinical trial that enrolledpatients with previously untreated (other than with interleukin-2) BRAF V600E-mutated stage IV melanoma." (PMID 25089220, 2014). "In clinical practice in the US, most metastatic melanomas are tested for BRAFv600 mutations, and treated with a BRAF inhibitor if positive." (PMID 25198196, 2014). "Activating mutations of the serine threonine kinase, BRAF, were first identified in melanoma and cluster at the hot spot V600E site." (PMID 25009801, 2014).
melanoma (continued). "CH5126766/RO5126766 induced G1 cell cycle arrest in two melanoma cell lines with the BRAF V600E or NRAS mutation." (PMID 25422890, 2014). "ERK1/2 is constitutively activated in melanomas and correlates with high frequencies of activating BRAF mutations." (PMID 24466036, 2014). "Vemurafenib is the first FDA-approved BRAF inhibitor for the treatment of BRAFV600E mutation–positive advanced melanoma." (PMID 26328215, 2014). "Current pharmacokinetic data are based on a pooled analysis of 458 patients with BRAF mutation–positive advanced melanoma following 15 days of vemurafenib at 960 mg twice daily." (PMID 26328215, 2014). "Multiplex primer extension assays were performed to detect the BRAF c.1799 T > A (p.V600E) mutation in melanomas (n = 7), colorectal carcinomas (n = 2), papillary thyroid carcinoma (n = 1) and a case of Langerhans histiocytosis." (PMID 25067909, 2014). "This was first studied in vitro, where treatment of BRAF-mutant melanoma cell lines was associated with a significant increase in expression of Melanocyte Differentiation Antigens (MDA), including MART-1, gp-100, TYRP-1 and TYRP-2." (PMID 29250602, 2014). "That the cellular network is chief player is also indicated by experiments: genome-wide analysis of DNA copy number and somatic mutation frequencies in melanoma BRAF data revealed significant differences." (PMID 25277176, 2014). "Mutations in BRAF have been reported in up to 60% of melanoma cases, between 40 to 70% of thyroid carcinomas, and up to 18% of CRCs." (PMID 25361007, 2014). "In the experience of our institution, thirty-two BRAF mutated melanomas (32%) were detected among 99 melanomas screened for genetic mutations." (PMID 24591764, 2014). "BRAF (v-Raf murine sarcoma viral oncogene homolog B) mutations and BRAF inhibitors first gained attention in melanoma where 40–60% of tumors harbor activating V600E BRAF mutations." (PMID 25505733, 2014). "This is consistent with the observation that BRAF-mutated melanomas more frequently affect younger individuals with lower cumulative ultraviolet exposure." (PMID 24959217, 2014). "BRAF mutations were identified in 109/229 (48%) primary melanomas, whereas cKIT and CyclinD1 amplifications were observed in 10/216 (5%) and 29/214 (14%) tumor tissues, respectively." (PMID 24885594, 2014). "Here, we report a patient with BRAF V600E-mutated stage IV melanoma who developed a severe leukopenia upon targeted therapy with the BRAF inhibitor vemurafenib." (PMID 25526431, 2014). "BRAF mutations have been identified at a high frequency in specific cancers, including approximately 50 to 60% of melanoma." (PMID 25037456, 2014). "A recently published randomized controlled trial has shown that inhibitor (BRAF and MEK) kinase improved rates of overall and progression-free survival in patients with previously untreated melanoma with the BRAF V600E mutation." (PMID 25205351, 2014). "BRAF mutations are more frequent in melanomas that develop in intermittently sun-exposed skin and less so in acral and mucosal melanomas." (PMID 24743024, 2014). "The patients’ age at diagnosis of stage III melanoma was significantly lower in tumors with BRAF mutations in contrast to patients with NRAS mutations, who were on average older." (PMID 24959217, 2014). "This mutation represents around 90% of BRAF mutations described in melanoma and occurs in approximately 50% of melanoma cases." (PMID 25074438, 2014). "The reported results of trials with selective oral BRAF inhibitors showed efficacy in melanoma patients with BRAFV600E mutations." (PMID 24743024, 2014). "BRAF is a serine/threonine kinase that is mutated and constitutively activated in ~60% of melanoma patients." (PMID 24980819, 2014). "A high prevalence of somatic mutations in BRAF gene was detected in incident and subsequent melanomas." (PMID 24885594, 2014).
melanoma (continued). "In a mouse model study, NF1 mutations cooperate with BRAF mutations in the pathogenesis of melanomas by preventing oncogene-induced senescence." (PMID 25026295, 2014). "In fact, large, recent studies have shown that the p.V600E genotype is not as prevalent as expected and that p.V600K and p.V600R respectively account for 17%-22% and 3%-4% of the BRAF mutation-positive melanoma population." (PMID 25265970, 2014). "One (0.4%) out of 229 melanoma samples presented a coexistence of BRAF mutation and cKIT amplification, confirming that aberrations in these two genes can be considered as mutually exclusive." (PMID 24885594, 2014). "50% of melanomas harbour activating mutations in the kinase BRAF, the most common being a V600E substitution, and 25% harbour mutations in the GTPase NRAS." (PMID 24941944, 2014). "Although the high frequency of BRAF mutations (and particularly the p.V600E mutation) in melanoma has been confirmed in all subsequent studies, its incidence is usually somewhat lower than initially reported." (PMID 25265970, 2014). "According to the COSMIC database (Catalogue Of Somatic Mutations In Cancer, Dec 2013) 44% of the melanomas harbor BRAF mutations and 97.1% of these mutations are localized in codon 600 of the BRAF gene." (PMID 24410877, 2014). "BRAF mutations have been analyzed using meta-analysis studies in melanoma, colorectal cancer and papillary thyroid cancer." (PMID 24979348, 2014). "A breakthrough in melanoma therapy was provided by the discovery that up to 66% of malignant melanomas are mutated in BRAF." (PMID 25557167, 2014). "Since patients diagnosed with BRAF V600E and V600K mutated advanced melanoma show response to treatment with MAP kinase inhibitors, several sensitive methods have been developed to determine the V600 allele status of melanoma patients." (PMID 25037456, 2014). "Molecular analysis showed the melanoma harbored a GNAQ mutation with wild-type BRAF, KIT and NRAS genes." (PMID 25030020, 2014). "Clinical variables in this study included tumour anatomical site, tumour thickness, tumour subtype, solar elastosis score, pigmentation scores and BRAF/NRAS mutation status (known oncogenic drivers in melanoma)." (PMID 24752294, 2014). "Mutations in the activation segment of the v-raf murine sarcoma viral oncogene homolog B (BRAF) gene are present in approximately 50% of melanomas." (PMID 25265970, 2014). "BRAF inhibitors, such as vemurafenib and dabrafenib, demonstrate clinical benefit in melanomas harboring the BRAF p.V600E mutation and MEK inhibitors act in the presence of BRAF and NRAS mutations." (PMID 24959217, 2014). "The BRAF and NRAS genotype distribution in the nodal metastases of cutaneous melanomas is identical to that observed in stage IV melanoma, with BRAF p.V600E as the most frequent mutation harbored by melanoma cell metastases in lymph nodes." (PMID 24959217, 2014). "BRAF mutations were detected in 154 of 250 (61.6%) melanoma nodal metastases and were predominantly p.V600E mutations." (PMID 24959217, 2014). "Vemurafenib exhibits an approximately 30-fold selectivity for p.V600E mutated compared to wildtype BRAF melanomas." (PMID 24410877, 2014). "A recent publication has reported a patient with BRAF-mutated melanoma who developed progressive disease in the brain and pelvic lymph nodes after single-agent vemurafenib treatment." (PMID 25610709, 2014). "While new treatments targeting specific melanoma driver mutations such as BRAF V600E have a significant impact, the benefit of treatment is often short lived and the disease becomes rapidly fatal once resistance develops." (PMID 25051363, 2014). "The introduction into the clinical practice of vemurafenib and dabrafenib, potent inhibitors of BRAFV600 mutants, makes the assessment of BRAF mutations as a crucial step toward the appropriate use of a targeted melanoma treatment." (PMID 24885594, 2014).